CDK5R2-AS1 (CDK5R2 antisense RNA 1)
Synonyms: LINC01494
Gene: Long non-coding RNA gene on chromosome 2 (218,899,739 to 218,962,135, reverse strand). Ensembl gene ENSG00000235024.
Diseases named in the same sentence as CDK5R2-AS1 in open-access papers:
CDK5R2-AS1 is named in the same sentence as 1 disease in open-access papers, as found by Europe PMC text mining. Sharing a sentence is not in itself a finding about the gene and the disease.
CDK5R2-AS1 shares sentences with these, for which no sentence is quoted: glioma (1 paper).